ICAM1 (intercellular adhesion molecule 1)
Diseases named in the same sentence as ICAM1 in open-access papers (continued):
Sharing a sentence is not in itself a finding about the gene and the disease.
astrocytoma (4 papers, 2013 to 2024). "Other proteins overexpressed in astrocytomas have also been implicated in tumor growth and invasion, such as the inter-cellular adhesion molecule 1 (ICAM-1), the neural cell adhesion molecule NCAM1 and the thrombomodulin (THBD)." (PMID 25360666, 2014). "α-syn also strongly upregulates IL6 and inflammatory mediator intercellular adhesion molecule-1 (ICAM-1) in human astrocytes and in a human U-373 MG astrocytoma cell line, which is further linked to the activation of the major mitogen-activated protein kinase (MAPK) pathway." (PMID 34575087, 2021). "Moreover, cannabinoid receptor-independent inhibition of VCAM-1 and ICAM-1 expression is not new and has previously been described in astrocytoma cells using the synthetic cannabinoid R(+)WIN 55.212-2, where inhibition of transactivation of NF-κB was shown to be the underlying mechanism." (PMID 39768198, 2024).
bacterial meningitis (4 papers, 2007 to 2025). Inflammation of the membranes surrounding the brain and spinal cord due to a bacterial infection. "The cell walls of Streptococcus pneumoniae (PCW), the most common cause of adult bacterial meningitis, also induces ICAM-1 expression in rat primary brain microvascular endothelial cell cultures." (PMID 22768975, 2012). "Elevated intrathecal, but not serum, levels of soluble ICAM-1 have been reported in inflammatory neurological conditions such as viral meningoencephalitis and bacterial meningitis." (PMID 40948499, 2025). "Our findings demonstrated the roles of PDGF-B and ICAM-1 in mediating bacterial-induced BBB damage as well as neuroinflammation, providing new concepts and potential targets for future prevention and treatment of bacterial meningitis." (PMID 31092253, 2019). "This induction could be completely blocked by TNF-α antibody, suggesting that ICAM-1 expression is mediated by the inflammatory cytokine and that cerebral endothelial cells regulate critical steps in inflammatory BBB disruption of bacterial meningitis." (PMID 22768975, 2012).
cerebrovascular disease (4 papers, 2017 to 2024). "In addition to these results, the current study reveals a significant association of serum and urinary mtDNA levels with pro-inflammatory biomarkers TNFα and ICAM-1, which intervene in the pathogenesis of both DKD and cerebrovascular disease." (PMID 38672515, 2024).
childhood asthma (4 papers, 2014 to 2024). "published the first article in this field, which revealed that the expression levels of ICAM-1 and L-selectin on peripheral blood NK cells decreased during acute attacks of childhood asthma." (PMID 38384457, 2024). "In an integrative genomic approach, data suggested that ICAM-1 was likely to be involved in the development of childhood asthma." (PMID 37013496, 2023). "Interactions between the human intercellular adhesion molecule 1 (ICAM1) polymorphisms and ETS have also been associated with risk of childhood-onset asthma." (PMID 31921716, 2019). "The association between polymorphisms of the gene encoding intercellular adhesion molecule 1 (ICAM1) and gene-environment interactions with childhood asthma has not been fully investigated." (PMID 25003170, 2014).
co-infection (4 papers, 2014 to 2025). "The TAK-242/siRNA-treated IAV+SA group exhibited markedly decreased mRNA levels of inflammatory factors (NF-κB, IL-6, TNF-α) and adhesion molecules (ICAM-1, VCAM-1) compared with the uninfected IAV+SA group, confirming TLR4 as the key receptor mediating co-infection-induced inflammation." (PMID 40572089, 2025). "While Intercellular adhesion molecule-1 (ICAM-1) overexpression has been shown to be independent of ECM, the phenomenon can be appreciated in the case of human B. duttonii and P. falciparum co-infection as a pro-sequestration driven process." (PMID 25075973, 2014).
colorectal tumors (4 papers, 1998 to 2016). "These eight isoforms encoded by OGDH, COL6A3, ICAM1, PHPT1, PPP2R5D, SLC29A1, and TRIB3 genes were up-regulated in colorectal tumors, and this is in concordance with the bioinformatics data." (PMID 28105922, 2016). "We also observed that the distribution of ICAM-1 was exclusively extracellular in all colorectal tumors." (PMID 19822019, 2009).
cutaneous melanoma (4 papers, 2016 to 2025). A primary melanoma arising from atypical melanocytes in the skin. "In addition, cell adhesion molecules, including ICAM-1 and VCAM-1, have been implicated in tumor progression in cutaneous melanoma." (PMID 27314329, 2016).
cyst (4 papers, 2017 to 2024). A sac-like closed membranous structure that may be empty or contain fluid or amorphous material. "The ability of CP explants to generate cyst-like lumens after plating in Matrigel and the presence of tight junction markers ICAM-1, ZO1 and occludin indicates that CP explant cells provide intact barrier function." (PMID 32431599, 2020). "Some factors (e.g., ICAM1, CCL20, PSME2, AXL) can also enhance proliferative signaling pathways (via MAPK/ERK, JNK, and JAK/STAT signaling, among others) that lead to cyst growth stimulation." (PMID 38385746, 2024). "However, there was a tendency towards increased ICAM-1 levels in the group with radiologically active NCC (median 538,615 ± 95,383 pg/mL for active vs. 197,836 ± 65,315 pg/mL for inactive, adjusted p = 0.0826), suggesting a possible association with cyst activity." (PMID 39093864, 2024). "Key words:Periapical cyst, radicular cyst, residual cyst, transforming growth factor beta 1 (TGF-β1), intercellular adhesion molecule 1 (ICAM-1), ki-67." (PMID 27918735, 2017).
dermatitis (4 papers, 2017 to 2025). An inflammatory process affecting the skin. "The genes ICAM1 and STAT1 have associations with some skin disorders such as urticaria, and eczema, respectively." (PMID 39024368, 2024).
diabetic macular edema (4 papers, 2016 to 2024). "Endothelial damage due to accumulation of AGEs, activation of PKC, increased expression of VEGF and intracellular adhesion molecule (ICAM-1), increase in ROS leads to breakdown of BRB resulting in diabetic macular edema." (PMID 27847626, 2016). "ICAM1 and MCP1 are highly relevant to monitor in RVO and diabetic macular edema, but experiments using discovery proteomics generally do not identify ICAM1 and MCP1." (PMID 28452939, 2017).
E. coli infection (4 papers, 2016 to 2024). "Results revealed that PD exhibited a valid therapeutic approach for E. coli infection via the intestinal protection, as well as the inhibited release of IL-8 and ICAM-1." (PMID 32714880, 2020). "Our previous transcriptomics data suggested that ICAM-1 was sharply increased in hBMECs upon meningitic E. coli infection." (PMID 31092253, 2019). "In a previous study of transcriptomics data, we found that ICAM-1 was significantly increased in hBMECs upon meningitic E. coli infection, indicating activation of BMECs." (PMID 31092253, 2019). "Additionally, in accordance with the previous study which showed that PD effectively inhibited the expression of proinflammatory cytokines including IL-1beta, IL-6, and TNF-alpha, PD treatment also decreased IL-8 and ICAM-1 induced by E. coli infection in our work." (PMID 32714880, 2020). "These evidences indicate that ICAM-1 and VCAM-1 upregulation induced by meningitic E. coli infection depends on the activation of Egr-1." (PMID 38233877, 2024). "It has been shown that endothelial surface expression of ICAM-1 and CD44 is significantly elevated upon E. coli infection but expression of ICAM-2, VCAM-1 or E-selectin in pulmonary endothelial cells is not affected." (PMID 27657497, 2016). "Our previous RNA-sequencing data from human brain microvascular endothelial cells (hBMECs) revealed two important host factors: platelet-derived growth factor-B (PDGF-B) and intercellular adhesion molecule-1 (ICAM-1), which were significantly upregulated in hBMECs after meningitic E. coli infection." (PMID 31092253, 2019). "Meningitic E. coli infection could enhance BBB permeability via PDGF-BB-mediated TJ breakdown, and the infection-induced endothelial activation by ICAM-1 upregulation largely initiates the development of CNS inflammatory responses." (PMID 31092253, 2019).
eczema (4 papers, 2019 to 2025). "Studies have shown that shikonin may inhibit the expression of SP, NK-1R, and ICAM-1 in the skin tissue of eczema model mice, inhibit mast cell degranulation, and alleviate the symptoms of eczema inflammatory injury." (PMID 35907999, 2022).
esophageal squamous cell carcinoma (4 papers, 2015 to 2022). Esophageal squamous cell carcinoma (ESCC) is a type of esophageal carcinoma (EC) that can affect any part of the esophagus, but is usually located in the upper or middle third. "ICAM-1 increases the metastatic capacity of esophageal squamous cell carcinoma cells (ESCC) and stimulates tumorigenesis in a mouse model." (PMID 30657059, 2019). "Additionally, ICAM1 and CD44 may have compensatory effects to maintain the dry characteristics of esophageal squamous cell carcinoma, indicating multiple targeted therapies that can be combined and considered in cancer treatment." (PMID 32195055, 2020).
gallbladder cancer (4 papers, 2024 to 2025). "Fibrinogen is known to promote gallbladder cancer cell metastasis by inducing the expression of intercellular adhesion molecule 1 (ICAM1)." (PMID 38995895, 2024). "ICAM1 overexpression had been confirmed to accelerate the metastasis of gallbladder cancer cells." (PMID 40329406, 2025). "Previous studies have shown that fibrinogen induces the expression of intercellular adhesion molecule-1 (ICAM-1), promoting tumor cell migration, angiogenesis, and metastasis in various cancers, including gallbladder cancer." (PMID 40134599, 2025).
gastric ulcer (4 papers, 2011 to 2024). An ulcerated lesion in the mucosal surface of the stomach. "The current study aims to scout the modulatory effect of LF on the ROS/ICAM-1/Nrf2 signaling pathway in ethanol-induced gastric ulcers in rats." (PMID 36544526, 2022). "Short-term administration of lansoprazole in patients with gastric ulcers reduced the expression of intercellular adhesion molecule-1 on peripheral blood monocytes, thus reducing the chemotactic ability of the monocytes." (PMID 30200363, 2018). "The anti-inflammatory, anti-oxidant, and gastro-protective effects of β-Citronellol against indomethacin-induced gastric ulcer model in rats through mediating COX-I, COX-II, PGE2, 5-LOX, eNOS, and ICAM-1 inflammatory markers." (PMID 39342545, 2024).
glomerular diseases (4 papers, 2006 to 2023). "Since glomerular influx of immune cells plays a critical role in the development of some glomerular diseases, the mRNA expression of endothelial leukocyte adhesion molecules ICAM-1 and VCAM-1 in the renal cortex was measured." (PMID 37475889, 2023). "The designation of ICAM-1 as a minor contributor opens the possibility of other common cold viruses that bind receptors other than ICAM-1 (i.e., viruses other than rhinovirus A and B) in inducing relapse on human glomerular disease." (PMID 37795536, 2023). "Our results suggest that other factors, such as the activation of tubular cells indicated by the de novo expression of ICAM-1 and C5b-9, may be of importance, as is the case with other forms of glomerular diseases." (PMID 17078867, 2006). "Given the profibrotic effect of TGF‐β1 and the role of ICAM‐1 in initiating the inflammatory process, the increased shear stress––in combination with increases in hoop stress––may play a significant role in progression of glomerulopathy in the remaining glomeruli in severe renoprival conditions." (PMID 32951361, 2020).
gout (4 papers, 2021 to 2025). A condition characterized by painful swelling of the joints, which is caused by deposition of urate crystals. "The main pathological trait of gout is endothelial activation brought on by IL-1 and IL-6 while inducing ICAM-1 expression, which increases the influx of neutrophils into the joint fluid and the subsequent influx of monocytes." (PMID 36339594, 2022). "One study also found that the ethanol extract of P. igniarius can inhibit XO activity and relieve acute gout inflammation by down-regulating the expression of IL-1β and ICAM-1 in vitro." (PMID 35087407, 2021). "Subsequently, the enhanced accumulation of MLT‐MLP at gout‐afflicted sites, accompanied by the upregulated expression of ICAM‐1 and VCAM‐1 within the affected region, further corroborated our hypothesis." (PMID 39717013, 2025). "Previous reports have shown that AM had anti-inflammation, anti-oxidation, anti-tumor, and anti-virus functions, and inhibiting IL-1β and ICAM-1 by AM may lead to gout suppression in MSU-induced HUVECs." (PMID 34079466, 2021). "To corroborate the in vivo binding mechanism of MLT‐MLP, we undertook a comparative analysis of MLT‐MLP localization and the expression levels of ICAM‐1 and VCAM‐1 in both healthy and gout mice." (PMID 39717013, 2025). "A pronounced upregulation of ICAM‐1 and VCAM‐1 were observed in the gout‐afflicted paws in contrast to the normal paw." (PMID 39717013, 2025).
Graves disease (4 papers, 2014 to 2021). Graves' disease is an autoimmune disorder that leads to overactivity of the thyroid gland (hyperthyroidism).It is caused by an abnormal immune system response that causes the thyroid gland to produce too much thyroid hormones. "To understand the effects of the treatment for Graves’ hyperthyroidism on markers of vascular atherosclerosis, we examined newly diagnosed Graves’ disease patients and analyzed the level of adhesion molecules (ICAM-1, VCAM, E-selectin), PWV, and cIMT." (PMID 34987480, 2021).
HCMV infection (4 papers, 2012 to 2017). "These experimental results suggest that downregulation of SIRT1 by HCMV infection enhanced ICAM-1 expression, thereby inducing EC motility and tube formation." (PMID 24376725, 2013). "Nonetheless, it is known that HCMV infection of endothelial cells induces the expression of adhesion molecules ICAM-1 and VCAM-1 that serve to magnify transendothelial cell migration of inflammatory cells including monocytes." (PMID 22570607, 2012).
head and neck cancer (4 papers, 1999 to 2017). A primary or metastatic malignant neoplasm affecting the head and neck. "Analysis of ICAM-1 expression level in 48 human head and neck carcinomas, using the quick score method, was consistent with the quick score for the presence of the invasive cohorts of tumor cells observed in the tumor samples." (PMID 27901489, 2017). "Because our in vitro results suggest a novel role for ICAM-1 in tumor ECM remodeling and onset of proinvasive tumor stroma, expression of ICAM-1 was investigated in invasive tumor cell clusters in human head and neck carcinomas." (PMID 27901489, 2017). "Rofecoxib, a COX-2–specific inhibitor, is known to increase monocyte binding to intracellular adhesion molecule-1 (ICAM-1) with concomitant enhancement of tumor tissue infiltration and restoration of immune function in head and neck cancer patients." (PMID 25680189, 2015).
hearing loss (4 papers, 2019 to 2024). "Upregulated expression of ICAM-1 was observed in both noise exposure and lipopolysaccharide-induced inner ear inflammation, leading to further hearing impairment." (PMID 39764513, 2024). "In noise-induced hearing loss, the damage to fibrocytes of the spiral ligament is likely to lead to changes in cytokines or chemokines such as TNF-a, IL-1b, IL-6, and Icam-1." (PMID 34150778, 2021). "As a TF, FOS may participate in inflammation by regulating its target genes, such as ICAM-1, CSF1 and CCL5 which were all important inflammatory proteins for hearing loss." (PMID 31149396, 2019).
hepatitis C (4 papers, 2018 to 2025). "A preliminary pilot study was carried out on the effect of δ-tocotrienol feeding in hepatitis C patients on six protease subunits (X, Y, Z, LPM7, LMP2 and LMP10), ICAM-1, VCAM-1, and TNF-α using total blood mRNA of these patients." (PMID 29606130, 2018). "In addition to that, effect of δ-tocotrienol on expression of proteasome subunits (X, Y, Z, LMP7, LMP2, LMP10), ICAM-1, VCAM-1, and TNF-α using total RNAs derived from plasmas of hepatitis C patients was investigated." (PMID 29606130, 2018). "Moreover, results of plasma total mRNAs after δ-tocotrienol feeding to hepatitis C patients revealed significant inhibition in the expression of pro-inflammatory cytokines (TNF-α, VCAM1, proteasome subunits) and induction in the expression of ICAM1 and IFN-γ after post-treatment." (PMID 30031388, 2018).
Hypoglycemia (4 papers, 2020 to 2026). A decreased concentration of glucose in the blood. "Ischemic insults, including hypoxia and hypoglycemia, trigger a signaling cascade that upregulates the expression of endothelial adhesion molecules, such as intercellular adhesion molecule-1 (ICAM-1) and vascular cell adhesion molecule-1 (VCAM-1)." (PMID 39063126, 2024). "Others reported increased levels of VEFGA, ICAM1 and VCAM1 50 min post hypoglycemia (3.2 mmol/L) in T2D." (PMID 41596469, 2026). "Similar suppression of ICAM-1 was observed in hypoxia–hypoglycaemia models, where HBOT reduced ICAM-1 mRNA and protein and limited neutrophil binding via NOS-regulated pathways." (PMID 41462642, 2025). "Our results are in accordance with others who showed no changes in ICAM1 and VCAM1 post hypoglycemia." (PMID 41596469, 2026).
intracerebral hemorrhage (4 papers, 2014 to 2025). A cerebrovascular disorder characterized by bleeding into one or both cerebral hemispheres including the basal ganglia and the cerebral cortex. "Research by Aihara and Kasuya has shown that expression levels of IL-6, IL-1α, and Intercellular Adhesion Molecule-1 (ICAM-1) following intracerebral hemorrhage correlate with the onset of CVS." (PMID 39981435, 2025). "The over-expression of ICAM-1 mRNA has been detected at 3 hours, peaks at 6 hours and persists to 5 days of reperfusion after middle cerebral artery occlusion, as well as after intracerebral hemorrhage." (PMID 25389378, 2014).
kidney inflammation (4 papers, 2013 to 2022). "Kidney inflammation is associated with increased production of pro-inflammatory mediators, and up-regulation of adhesion molecules such as Intercellular adhesion molecule-1 (ICAM-1) and vascular cell adhesion molecule-1 (VCAM-1)." (PMID 24896770, 2014). "A previous study has showed CD2AP binds to intercellular adhesion molecule-1 to regulate mechanical signal transduction, leukocyte adhesion, and exerts an important role in kidney inflammation." (PMID 35172672, 2022). "UUO kidneys show elevated expression levels of monocyte chemoattractant protein-1 (MCP-1), vascular cell adhesion molecule-1 (VCAM-1), and intercellular adhesion molecule-1 (ICAM-1), which promote monocyte infiltration and kidney inflammation." (PMID 23255047, 2013).
liver cirrhosis (4 papers, 2016 to 2024). "The aim of this study was to explore and correlate the behavior of sVAP-1 with that of the soluble vascular cell adhesion molecule-1 (sVCAM-1) and intercellular adhesion molecule-1 (sICAM-1) and with the severity of liver cirrhosis." (PMID 39000418, 2024).
lymphopenia (4 papers, 2016 to 2021). Reduction in the number of lymphocytes. "Less pronounced lymphopenia (p = 0.02), a trend towards a lower expression of CD69 count (p = 0.07), and antigen-stimulated ICAM-1 (p = 0.01) were found in the verum group." (PMID 27478305, 2016).
metastatic carcinoma (4 papers, 2013 to 2023). A carcinoma which has spread from the original site of growth to another anatomic site. "Notably, FBXO4 shows specificity towards ICAM-1 and may have different ubiquitin-dependent regulatory roles such as the suppression of metastatic cancer progression via diverse pathways." (PMID 29137327, 2017).